INS (insulin)
Diseases named in the same sentence as INS in open-access papers (continued):
Sharing a sentence is not in itself a finding about the gene and the disease.
Obesity (continued). "In overall nonparametric longitudinal analysis, serum concentrations of total cholesterol, HDL, LDL, triglycerides, insulin, HOMA‐IR, HbA1c (%) (p < 0.001) and TG/HDL ratio (p < 0.05) were higher among obese than in subjects without obesity." (PMID 40078195, 2025). "Genes related to insulin, PPAR signaling, and oxidative phosphorylation pathways were altered in individuals with obesity without T2D, while genes related to ribosome and spliceosome were changed in those with T2D." (PMID 40862085, 2025). "Meanwhile, the previous study showed that food restriction initiated at 6 weeks of age, a period at which obesity in BDNF heterozygous mice is not yet apparent, induced normalization of body weight, and serum glucose and insulin levels." (PMID 38672461, 2024). "Insulin, fasting glucose, HOMA-IR, and HbA1c were also higher in people with obesity, with no participants displaying prediabetes." (PMID 38762719, 2024). "Given the absence of obesity in this double-hit GDM model, the results clearly indicate that impaired insulin secretion driven pregnancy hyperglycaemia has a distinct contribution to the development of postpartum MASLD." (PMID 38918525, 2024). "Administration of Bifidobacterium animalis IPLA R1 decreased serum insulin levels with no significant variation in FGB and HOMA index in mice of a short-term diet-induced obesity." (PMID 39456659, 2024). "Collectively, although the impact of GHSR deficiency was observed during the early stages of HFD administration, it did not significantly alter insulin secretion, glucose intolerance, nor insulin sensitivity in HFD-induced obesity." (PMID 38794702, 2024). "There were obesity, but not sex, differences in the insulin regulation of splanchnic FFA release as well as evidence of both obesity and sex effects in the insulin regulation of UBNS lipolysis." (PMID 38602778, 2024). "IRF3 levels are increased in the adipocytes of people and mice with obesity, and mice lacking IRF3 in all tissues show improved insulin sensitivity before body weight divergence after high fat feeding." (PMID 38816388, 2024). "In children with obesity, adipocyte hypertrophy often leads to elevated serum FFA levels and accumulation of fatty acids in nonadipose tissues due to the weakening of insulin's antilipolytic effect." (PMID 40302954, 2024). "However, it appears that reduced genomic stability in obesity is not due to lipid accumulation per se, but it is the consequence of several factors that commonly accompany the condition, such as chronic inflammation, oxidative stress and altered insulin sensitivity/glucose uptake." (PMID 39033117, 2024). "Eighteen people with obesity and 18 nonobese controls were studied with [18F]FDG positron emission tomography during insulin clamp." (PMID 37955868, 2024). "Similar to our study, in Korean elderly, non-sarcopenic non-obese individuals had lower insulin levels and HOMA-IR compared to those with obesity, with or without sarcopenia, as well as in sarcopenic elderly, HOMA-IR was higher in both obese and non-obese." (PMID 38612998, 2024). "Another study indicated a non-significant improvement in insulin levels and Homeostatic Model Assessment (HOMA) indices in individuals with obesity, but it found significantly decreased total cholesterol and LDL cholesterol after inulin supplementation." (PMID 39056692, 2024). "Interestingly, not only the tyrosine kinase pathway triggered by insulin might contribute to this metabolic decision, since mice characterized by adipocyte-specific deletion of IGFR1, or of Axl showed also protection against HFD-induced obesity and enhanced BAT thermogenesis in mice." (PMID 39594650, 2024). "Patients with obesity exhibited higher uACR, HbA1c, HOMA-IR and fasting glucose, insulin and hsCRP levels and lower HDL-cholesterol levels compared to patients without obesity (all p < 0.001)." (PMID 38755195, 2024).
Obesity (continued). "Resveratrol further increased IRS1, Akt, and TBC1D4 insulin-stimulated phosphorylation and SIRT1 content in myotubes from lean women, but not in women with severe obesity." (PMID 38324260, 2024). "For example, dietary supplementation with a glycomacropeptide derived from casein for 12 weeks decreased insulin and HOMA-IR but did not protect against high-fat/high-sugar diet-induced obesity or improve OGTT in C57BL/6 mice." (PMID 39272602, 2024). "LY2405319 treatment of patients with obesity and T2DM for 28 days improved dyslipidemia, lowered body weight, reduced insulin levels, and increased adiponectin levels but did not result in the expected glucose-lowering effects." (PMID 37260446, 2023). "Neither of these studies assessed the effect of mare weight or insulin status on the growing embryo, as mare BCS, other obesity measurements or insulin concentrations were not reported." (PMID 37152686, 2023). "Croymans and colleagues reported improved insulin sensitivity, lean body mass, relative strength as well as GLUT4 expression in overweight individuals and/or individuals with obesity after 12 weeks of resistance training (3 times/week) at normoxia." (PMID 36441492, 2023). "Individuals with obesity had higher levels of Gal-4, were older, had a higher BMI, higher levels of NT-proBNP, GIP, triglycerides, insulin, and FPG, along with higher HOMA-IR, compared to individuals without obesity." (PMID 37985679, 2023). "P38 MAPK can promote glucose transport in an insulin-independent manner and mice lacking ERK1 have been reported to show resistance to diet-induced obesity." (PMID 36837893, 2023). "Obesity, T2DM duration > 5 years, albuminuria, CKD, hypertriglyceridemia, as well as using insulin both with and without oral GLDs were independently associated with the prevalence of anemia among our participants." (PMID 36894956, 2023). "In this randomized clinical trial of adults with obesity and NAFLD, a TRE regimen did not achieve additional benefits for reducing IHTG content, weight, body fat, and metabolic risk factors compared with DCR, whereas TRE might be more effective in improving insulin sensitivity than DCR." (PMID 36930148, 2023). "Compared with children without obesity from 4 to 9 years, the incident- and stable-with-GO participants at 9 years presented lower values of Col-HDL and higher values of TG, TG/HDL ratio, insulin, HOMA-IR and BP." (PMID 36639534, 2023). "It has also been established that insulin sensitivity is reduced by ~40% in PCOS women, independent of obesity, although obesity further impairs insulin metabolism." (PMID 37893164, 2023). "For example, a transfer of healthy microbiota attenuated body weight gain and improved insulin response in PCOS models of female mice), whereas did not prevent ovariectomy-dependent obesity." (PMID 36387852, 2022). "A significantly lower risk of bacterial pneumonia was observed in SU users than in nonusers in the female and male sex, age 60 to 80 years, no obesity, no smoking, CCI = 0, DCSI ≥ 1, OAD numbers = 1 or >3, and no insulin use." (PMID 36429732, 2022). "FMT has short-term or no benefit in improving insulin sensitivity and HOMA-IR in patients with obesity and MS." (PMID 35528013, 2022). "We present a pilot study of 28 participants in which we compare (i) MAGE as a proxy for glycemic variability and (ii) levels of insulin, insulin resistance, and glucometric data extracted from CGM in a cohort of adults with obesity vs. without obesity." (PMID 36570168, 2022). "BMI, WC, fasting serum insulin, and HOMA-IR were all significantly higher in the group with obesity than in the group without obesity (P < 0.05)." (PMID 36570168, 2022). "Among 154 patients with obesity with or without T2DM, the suppression of free fatty acids during a euglycemic-hyperinsulinemic clamp, a measure of hepatic insulin sensitivity, was negatively correlated with intrahepatic TG content." (PMID 36336684, 2022).
Obesity (continued). "Preserved insulin signaling, with phosphorylation of the insulin receptor and AKT (T473) was not impaired in adipocytes from individuals with obesity and hyperinsulinemia, despite a significant downregulation of GLUT4." (PMID 36483678, 2022). "Although they also showed that BCKDK inhibitor can increase BCKD activity, reduce plasma levels of BCAAs and BCKAs, and improve insulin sensitivity in DIO mice, this intervention did not reduce obesity." (PMID 35448521, 2022). "Whereas LAR grouped with obesity (WC, PBF, BMI z-scores) and IR markers (HOMA-IR and fasting insulin) rather than only IR markers." (PMID 35370951, 2022). "Similarly, the mechanism for the effect of magnesium on obesity is not obvious, but according to the related studies, magnesium intake has an inverse relationship with hyperinsulinemia, metabolic syndrome, and reduction of the disposal of insulin-mediated glucose." (PMID 36817069, 2022). "This study introduced a model of interacting glycerol and insulin dynamics in response to an OGTT and compared the dynamics of insulin acting on glucose and glycerol in a population of adolescent girls with obesity and with or without PCOS." (PMID 35991189, 2022). "Among the factors studied in this work, NOC has an established role in obesity; mice lacking NOC are resistant to diet-reduced obesity, accompanied by deficits in lipid metabolism, as well as by changes in glucose and insulin sensitivity." (PMID 35630580, 2022). "Both pre-pregnancy obesity and excessive GWG directly contribute to higher fasting glucose levels and negatively correlate with HDL-cholesterol levels and glucose-to-insulin ratio of neonates, regardless of neonatal adiposity." (PMID 35391836, 2022). "A significantly lower risk of cardiovascular events was observed in SU users than in nonusers in the female and male sex, age 60 to 80 years, no obesity, no smoking, CCI ≥ 1, DCSI ≥ 2, OAD numbers = 2–3, and insulin use." (PMID 36429732, 2022). "Insulin and HOMA-IR levels increased significantly with puberty in all groups: they were significantly higher in overweight and obesity, both No-MetS and MetS, groups than normal weight group." (PMID 36601007, 2022). "Although not an intrinsic defect of PCOS, obesity can interact with hyperandrogenism to worsen PCOS phenotypes and impair insulin sensitivity." (PMID 35012577, 2022). "Decreased peripheral insulin sensibility was also described in normal-weight girls with PCOS, although not as impaired as in girls with PCOS and obesity." (PMID 34071499, 2021). "Conversely, insulin did not alter irisin levels in patients with T2DM and obesity in a euglycemic–hyperinsulinemic clamp." (PMID 35392577, 2021). "In animal models of congenital T2DM (Goto–Kakizaki rats) without obesity, SG and IT resulted in decreased body weight and glucose levels, as well as increased ghrelin and GLP-1 levels and insulin sensitivity." (PMID 34903800, 2021). "The excess HFCS–water intake did not lead to obesity, but led to impaired glucose tolerance (IGT) due to insulin-secretion defect." (PMID 34066196, 2021). "While high-fat diet feeding induced obesity for huCETP mice and their wild-type littermates lacking CETP expression, insulin sensitivity was higher for female huCETP mice than for their wild-type littermates." (PMID 35082691, 2021). "Offspring from obesity-prone HFD-fed dams (OP-O), unlike the offspring from obesity-resistant HFD-fed dams (OR-O), had lower body weight and higher serum glucose, insulin and NEFA (C-O)." (PMID 33903707, 2021). "CDAHFD with insufficient methionine induced insulin sensitivity and enhanced NASH pathology, but without obesity." (PMID 34390210, 2021). "On contrary to the results of the current work, some previous studies reported significant high serum levels of sestrin 2 in obesity with/without T2DM but still showed significant positive correlations with BMI, serum levels of insulin, and HOMA-IR." (PMID 34344352, 2021).
Obesity (continued). "We compared frequency and severity of SRBDs in children with simple obesity and with PWS, both without and on recombinant human growth hormone (rhGH) treatment, and correlation of SRBDs with insulin resistance tests." (PMID 33670584, 2021). "Although obesity is not a critical component of EMS, since it was proved that lean horses also suffer for insulin resistance, involvement of adipose tissue deterioration in EMS and local inflammation seem to be indisputable." (PMID 33536069, 2021). "Mice with diet or genetically induced obesity and lacking FABP4 have lower plasma glucose, triacylglycerol and cholesterol and better insulin sensitivity than control littermates." (PMID 34638803, 2021). "Insulin levels were higher in normal-weight PLWH than in the HIV-uninfected group but not statistically significant, however, for the overweight/obesity PLWH group, insulin levels were significantly higher in comparison with the other three groups (p<0.0001)." (PMID 34019585, 2021). "The mechanism via which obesity enhances the hepatic expression and circulating levels of GPI-PLD is not known, but it seems independent of plasma insulin levels." (PMID 34959666, 2021). "The PA level was significantly lower in women (χ2 test, p = 0.005), lower education level (p<0.001), obesity (p = 0.005), a history of hypertension (p = 0.012) or CVD (p<0.001), insulin treatment (p<0.001) and non-drinker (p<0.001)." (PMID 33444338, 2021). "Thus, perhaps the ester forms of succinic acid may be beneficial in insulin‐mediated glucose disposal, but succinic acid, despite potential benefit on mitochondria, does not affect blood glucose regulation in diet‐induced obesity, or that only acute/intermittent treatments may prove beneficial." (PMID 33185326, 2020). "Surprisingly, the myeloid cell-specific deletion of Sptlc-2 did not prevent HFD-induced adipose tissue inflammation and insulin resistance, suggesting its dispensable role in NLRP3 inflammasome activation in obesity." (PMID 32545355, 2020). "While studies were carried out on obese men (insulin secretion/sensitivity in obesity (NCT02595684, phase IV/completed 2015) demonstrated that tadalafil administration for 28 days did not modify insulin secretion or insulin sensitivity." (PMID 33153226, 2020). "One of the most deleterious effects of obesity is the deposition of lipids in non-adipose tissues and hyperlipidenia-induced reactive oxygen species production leading to mitochondrial dysfunction in insulin-responsive tissues which might promote inhibition of insulin action." (PMID 33344504, 2020). "In summary, current evidence suggests that obesity increases SNA in males, but not females, in part because of differential responsiveness to insulin." (PMID 32160920, 2020). "Nowadays, almost 30 years later, the link between obesity, diabetes and chronic inflammation has been confirmed and it has been also proved that mice lacking functional TNF-α are more insulin sensitive and glucose tolerant than wild type animals." (PMID 33114564, 2020). "We previously demonstrated that 8 weeks HF led to blunting of both insulin and IGF-1-mediated vasorelaxation of the aorta;2 however, this study did not examine the effect of obesity on resistance vessel function." (PMID 30295509, 2019). "We cultured HUVECs in conditions aiming to recapitulate different components of the obesity phenotype including elevated: insulin, IGF-1, glucose with and without insulin, angiotensin II, hydrogen peroxide and TNF-α for 24 h." (PMID 30295509, 2019). "Nevertheless, one study comparing adolescent males 12 to 19 years old with and without obesity and T2DM showed that insulin sensitivity was an independent predictor of testosterone levels." (PMID 31052376, 2019). "The glucose tolerance profile, AUC, insulin levels and HOMA-IR were also not affected by exposure to obesity." (PMID 30949067, 2019).
Obesity (continued). "According to the 7 studies investigated correlation between fasting insulin and RS supplementation, although level of fasting insulin was lower than control group in T2DM and obesity, most studies showed with no statistical significance." (PMID 31760943, 2019). "Until now, within the population of youth with obesity, children with MHO have been identified based either on the absence of MS components, preserved insulin sensitivity, or by various combinations of these criteria." (PMID 31920976, 2019). "However, it was not directly examined in our study whether or not the MLB-mediated amelioration of aging or obesity-induced ER stress, inflammasome formation, and disrupted insulin signaling are mediated through activating PPARβ/δ or through different mechanisms independent of PPARβ/δ." (PMID 30134566, 2018). "Hypoglycemic drugs and pharmacologic insulin do not have a large impact on SUA concentration, but obesity seems to be the primary determinant of SUA levels in T2DM patients." (PMID 30349765, 2018). "The results of glucose metabolism disorders in our study suggested that the severe OSA group had higher HOMA-IR and insulin levels than the mild-to-moderate OSA group independent of age, gender, obesity, diabetic duration, and antidiabetic therapies." (PMID 30671481, 2018). "Given the crucial role of SIRT1 in obesity, it is no surprise that emerging evidence suggests SIRT1 within the brain controls the systematic regulation of glucose/insulin homeostasis." (PMID 30532738, 2018). "A macrophage-specific knockdown of the immune response restores insulin sensitivity and ameliorates the lifespan shortening, but nevertheless, does not ameliorate the HFD-induced obesity." (PMID 29954158, 2018). "In our study, the severe OSA group had higher HOMA-IR and insulin levels in patients with OSA and T2DM independent of age, gender, obesity, diabetic duration, and antidiabetic therapies." (PMID 30671481, 2018). "Importantly, depletion of visceral AT T cells in diet-induced obese mice improved AT inflammation and systemic insulin sensitivity in young but not adult mice, suggesting an early window of time during which T cell-mediated immune function may be controlled in obesity." (PMID 29186929, 2017). "Though GNB3-T/+ mice did not have glucose intolerance prior to obesity, 5-week old female GNB3-T/+ mice had elevated fasting blood glucose, and both female and male GNB3-T/+ mice had elevated fasting plasma insulin." (PMID 29206867, 2017). "In contrast to the lack of an anti-obesity effect in Leprdb mice, FEN decreased fasting hyperglycaemia and glucose intolerance and increased pancreatic islet mass and circulating insulin." (PMID 28256636, 2017). "In addition, analysis of IVGTT data revealed subtle alterations in insulin sensitivity and beta cell function during pregnancy in the RYGB group vs the normal weight control group, which could be explained by their higher degree of pre-gestational overweight and obesity." (PMID 28918470, 2017). "Concomitantly, in normal weight conditions, but not in obesity, a decrease in the pro-inflammatory cytokine MCP-1 facilitates insulin action in the muscle." (PMID 28582461, 2017). "On the other hand, adipose tissue-specific knock-out of AR resulted in hyperinsulinemia in the absence of obesity, and when fed an HFD, the adipose tissue-specific AR knock-out mice developed obesity, hyperglycemia, and impaired insulin secretion." (PMID 26971100, 2016). "An explanation for the reverse expression direction of some obesity relevant genes could be that the Göttingen minipigs in this study represent a more healthy obese phenotype since they do not have significant differences in plasma lipids and insulin resistance." (PMID 27902747, 2016). "T2DM is characterized by obesity, insidious onset, family history of T2DM, residual insulin secretion, and the absence of antibodies against β-cells." (PMID 27992493, 2016).